CCL20 (C-C motif chemokine ligand 20)
Diseases named in the same sentence as CCL20 in open-access papers (continued):
Sharing a sentence is not in itself a finding about the gene and the disease.
breast cancer (continued). "Combinatorial immunotherapeutic approaches aiming at blocking CCL20 and depleting FOXP3 might improve therapeutic efficacy in breast cancer patients." (PMID 31852159, 2019). "In addition, a significant correlation was observed between CCL20 expression and FOXP3+ TILs infiltration in breast cancer tissue (rs = 0.359, P < .001)." (PMID 31852159, 2019). "Our results illustrated C-C motif chemokine ligand 20 (CCL20) was significantly elevated during taxane-containing chemotherapy in breast cancer patients with nonpathologic complete response." (PMID 30052635, 2018). "In contrast with the findings for GM-CSF, ELAVL1 and CCL20 expressions were markedly increased in breast tumor tissues and ELAVL1 expression showed a strong positive correlation with CCL20 expression in breast cancer subtypes, particularly the basal-like subtype." (PMID 28851919, 2017). "In the present study, we assessed the expression of CCR6, CCR7 and their ligands CCL19, CCL20 and CCL21 using immunohistochemistry in a series of tumors prospectively collected from patients with loco-regional breast cancer treated at the Centre Léon Bérard in 1996 and 1997." (PMID 21624121, 2011). "In their model, as in human breast carcinomas which secrete high levels of CCL20, attracted DCs to the tumor site did not mature." (PMID 19340288, 2009). "Some studies have indicated that tumor-secreted CCL20 activates granulocyte–monocyte progenitor cell differentiation through its receptor CCR6, leading to the expansion of PMN-MDSCs, which activates the CXCR2/NOTCH1/HEY1 signaling pathway to increase ALDH+ breast cancer tumor stem cells." (PMID 40722739, 2025). "Furthermore, utilizing qRT-PCR, in vitro LDA, and AIG assay, we also confirmed that CXCL2 neutralizing antibody inhibited breast cancer cell stemness promoted by CCL20-modulated PMN-MDSCs, suggesting CCL20-modulated PMN-MDSCs promoted the cancer cell stemness by secreting amounts of CXCL2." (PMID 36859354, 2023). "The downregulated C-C motif chemokine ligand 20 (CCL20) in NRP-1 KO cells was also studied in taxane-containing chemotherapy in triple-negative breast cancer (TNBC), and the elevated levels of CCL20 were shown to stimulate breast cancer stem-like cells through protein kinase C (PKC)." (PMID 37175499, 2023). "For example, CCL20 promoted the secretion of MMP2/9 and cell invasion ability in the basal-like triple-negative breast cancer cell lines, and treatment of anti-CCL20 antibodies could block the osteolytic breast cancer bone metastasis in mice." (PMID 35864953, 2022). "As tumour tissues express CCL20 at the mRNA level and EGFR/Ras signalling upregulates CCL20 expression, we next performed immunohistochemical analysis of CCL20 protein expression and ERK activation in serial sections of tumour samples from breast cancer, melanoma and HNSCC patients." (PMID 32601464, 2020). "Surgically resected samples from 156 patients with invasive breast cancer (BC) were assessed for the expression of FOXP3 and CCL20 by immunohistochemistry." (PMID 31852159, 2019). "In addition, ELAVL1 expression showed a strong positive correlation with CCL20 expression but not with CSF2 or CCR6 expression in breast cancer subtypes, particularly the basal-like subtype." (PMID 28851919, 2017). "Furthermore, CXCR2 antagonist SB225002 combined with DTX in vivo not only dramatically inhibited the tumor growth but also significantly decreased stemness of breast cancer cells, suggesting CXCR2 may be a potential therapeutic target for breast cancer patients with high expression of CCL20." (PMID 36859354, 2023). "Although this study did not establish any tumor-promoting effect of CCL20 via notch signaling, the independent role of notch and CCL20 makes it logical to assume that CCL20 may influence tumor progression via notch pathway in breast cancer." (PMID 34569432, 2021).
breast cancer (continued). "In addition, there are other GPCRs and ligands that may recruit Tregs, such as CCR5/CCL5 in colorectal cancer (CRC) and pancreatic cancer, CCR6/CCL20 in HCC and breast cancer, and CCR10/CCL28 in ovarian cancer, while CXCR3 and CXCR6 are expressed by Tregs infiltrating renal cell carcinoma." (PMID 25110692, 2014). "Although CCL20, a ligand of CCR6, was detectable in breast cell culture and frozen breast cancer tissue, it was not detectable in any paraffin embedded tumor samples in this series." (PMID 21624121, 2011).
hepatocellular carcinoma (56 papers, 2009 to 2026). A malignant tumor that arises from hepatocytes. "Elevated CCL20 expression has also been associated with poor prognosis in hepatocellular carcinoma (HCC) patients following curative resection." (PMID 41357186, 2025). "High expression of CCL20 is also closely associated with poor clinical outcome of patients with gliomas and with a poorer prognosis in patients with hepatocellular carcinoma." (PMID 23800251, 2013). "In addition, CCL20 has been implicated in the upregulation of vimentin in hepatocellular carcinoma, which supports our findings that vimentin was significantly increased in diabetic AFBs due to calcified plus AGEs diabetic VSMC CM treatment." (PMID 36835011, 2023). "For instance, DDR2 expression is upregulated in oxaliplatin-resistant hepatocellular carcinoma cell lines and induces chemoresistance by inducing C-C motif chemokine ligand 20 (CCL20) via STAT3 activation." (PMID 39766183, 2024). "Differential CCL20 promoter methylation was identified in different T cell subsets and in hepatocellular carcinoma (HCC) samples, correlating with mRNA expression levels." (PMID 36776856, 2023). "We analyzed the expression of interleukin 32 (IL-32) and chemokine CC ligand 20 (CCL20), which are known to be linked with inflammation and fibrosis, and for their expression in MASLD and hepatoma cells." (PMID 37686029, 2023). "Treatment with the saturated fatty acid palmitic acid (PA) induced mRNA and protein expression of IL-32 and CCL20 in hepatoma cells." (PMID 37686029, 2023). "The CCL20 expression has been reported to be up-regulated in many cancers, such as hepatocellular carcinoma and pancreatic cancer." (PMID 36045408, 2022). "Hepatocellular carcinoma (HCC) cells promote the chemoattraction of CCR6+ B lymphocytes by secreting CCL20 and facilitate cancer development by enhancing angiogenesis." (PMID 35841069, 2022). "Hypoxia-induced EMT in hepatocellular carcinoma leads to the increase in CCL20 secretion by hepatocellular carcinoma cells, which induces the co-cultured macrophages to express indoleamine 2,3-dioxygenase (IDO)." (PMID 35548187, 2022). "These outcomes were consistent in a study where the neutralization of CCL20 inhibited angiogenesis in hepatocellular carcinoma." (PMID 34569432, 2021). "Only one report has proven that Th9 cells can serve a tumor-promoting role in human hepatocellular carcinoma (HCC) via the CCL20 and STST3 signaling pathways." (PMID 32228589, 2020). "In hepatocellular carcinoma cells and murine colonic epithelial cells, CCL20 expression is known to depend on the ERK pathway." (PMID 31936670, 2020). "These include evaluation of the CXCL12/CXCR4 axis in angiogenesis, the CCL20/CCR6 axis in the growth of the hepatoma cell line Huh7; and the CCL5/CCR1 axis in promoting the metastasis and invasion of HCC cells." (PMID 32260550, 2020). "High EMT/hypoxia‐associated CCL20 expression has been associated with poor patient DFS and OS in a cohort of 90 hepatocellular carcinomas." (PMID 28599100, 2017). "In accord with the requirement of IL-36γ biological activity for efficient CCL20 induction in vivo, we observed upregulation of this chemokine by IL-36γ in cultured Huh7 hepatocellular carcinoma cells and primary macrophages." (PMID 25687687, 2015). "Up- regulation of CCL20 was demonstrated in human hepatocellular carcinoma tissues, and CCL20 expression was found to correlate with tumor grade." (PMID 19340288, 2009). "Consequently, we analyzed the gene expression of IL-32 and CCL20 in the liver tissue of controls and patients as well as the effect of fatty acids on their expression in hepatoma cells." (PMID 37686029, 2023). "Additionally, chemokine (C-C motif) ligand 20 (CCL20) derived from hepatoma cells that had undergone EMT induced IDO expression in monocyte-derived macrophages, which in turn suppressed T-cell proliferation and promoted the expansion of Tregs." (PMID 36823234, 2023).
hepatocellular carcinoma (continued). "Stimulation by CCL20 upregulated the mRNA level of CCR6 in hepatocellular carcinoma cells." (PMID 32418112, 2020). "As this signaling pathway is activated by CCL20 in hepatocellular carcinoma (HCC), it could be assumed that this occurs in melanoma cells as well, particularly CCL20 signals via the PI3K/AKT/mTOR pathway." (PMID 38730689, 2024). "To shed light on the role of cellular steatosis for the expression of IL-32 and CCL20 in MASLD, we treated two hepatoma cell lines, HepG2 and Huh7, with palmitic acid (PA, C16:0), known to induce cellular lipid accumulation, lipo-apoptosis and lipo-toxicity." (PMID 37686029, 2023). "Here, we present data showing increased expression of IL-32 and CCL20 in patients with MASH, as well as their induction by PA in hepatoma cells, likely mediated by oxidative stress and cellular lipid loading." (PMID 37686029, 2023). "LARC(CCL20) and his sole receptor CCR6 will favour migration of Treg cells into a tumour microenvironment and disease progression in hepatocellular carcinoma." (PMID 35108275, 2022). "In hepatocellular carcinoma (HCC), similar findings were demonstrated with increased CCR6+ Treg in the TME, which were inhibited with neutralizing mAb to CCL20." (PMID 31681327, 2019). "In our present study, we aimed to clarify whether CCR6/CCL20 was correlated with the migration of hepatocellular carcinoma (HCC)." (PMID 24743888, 2014). "In hepatocellular cancer, miR-21 was predicted to regulate “immune response” by targeting CD69, STAT3, CCL20 and SMAD7, in which STAT3 and SMAD7 are important signaling molecules for immune response." (PMID 24278370, 2013). "Furthermore, high CCL20 expression in patients with MASLD fibrosis contributed to the development of cholangitis and hepatocellular carcinoma." (PMID 38550602, 2024). "The study suggests that the Schisandra chinensis lignans and acteoside may counteract CCL20-induced epithelial-mesenchymal transition (EMT), invasion, and migration of hepatocellular carcinoma cells via the ERK1/2 pathway, while also promoting apoptosi." (PMID 39206194, 2024). "Additionally, co‐occurrence of CCL20 expression and EMT has been reported in hepatocellular cancer, as described in Section 2.2." (PMID 28599100, 2017). "Additionally, CCL20 can induce cell migration and epithelial-mesenchymal transition (EMT) through the PI3K/AKT and Wnt/β-catenin pathways, thereby promoting tumor growth and predicting low survival rates and tumor recurrence in hepatocellular carcinoma patients." (PMID 38550602, 2024).
melanoma (48 papers, 2009 to 2026). A malignant, usually aggressive tumor composed of atypical, neoplastic melanocytes. "Due to the observational nature of our study, the results do not allow for the interpretation of the causality and the molecular mechanism of CCL20 in melanoma patients." (PMID 38730689, 2024). "The presence of CCL20+ TAMS in melanoma tumours is associated with a poorer prognosis and reduced patient survival." (PMID 34830780, 2021). "To search for mechanisms underlying the CCL20/TNF/VEGFA secretory TAM phenotype associated with aggressive primary melanomas, and due to limited access to patient TAMs, we prepared tumor-conditioned macrophages." (PMID 34439098, 2021). "As shown by Parmenter and colleagues, CCL20 expression was significantly downregulated in a panel of oncogenic BRAF(V600) mutation-harbouring melanoma cell lines in response to treatment with the BRAF inhibitor vemurafenib." (PMID 32601464, 2020). "The high-CCL20 group contributed to a moderate risk increase with an HR of 1.99 (95% CI 1.21–3.29) (p = 0.007) regarding PFS in the advanced melanoma cohort, which is a stronger risk factor than elevated S100 at baseline (HR: 1.74, 95% CI: 1.05–2.90, p = 0.033)." (PMID 38730689, 2024). "Importantly, the high content of CCL20/TNF/VEGFA is strongly associated with a worse prognosis in primary melanoma patients." (PMID 34439098, 2021). "Interestingly, high CCL20 expression is associated with a shorter disease-free period and overall survival of melanoma patients." (PMID 30420855, 2018). "Further functional studies are required to gain a greater understanding of CCL20-associated signaling, demonstrate clinical impact in larger (multi-center) cohorts and discover potential new therapeutic targets, especially for advanced melanoma with resistance to ICI." (PMID 38730689, 2024). "Thus, we hypothesize that the CCL20 secretory TAM phenotype might be associated with melanoma progression and could be used for an accurate prognosis of metastatic risk in skin melanoma." (PMID 34439098, 2021). "In melanoma lung metastasis models, propionate upregulates CCL20 in pulmonary endothelial cells, recruiting Th17 cells via the CCL20/CCR6 axis to reduce metastasis." (PMID 41355959, 2026). "The CCL20 levels ranged from 0 pg/mL to 35.19 pg/mL with a median of 0.26 pg/mL (IQR: 3.1 pg/mL) in our advanced melanoma study cohort." (PMID 38730689, 2024). "Peripheral blood pDCs in stage I-III melanoma patients upregulated CCR6, a skin homing receptor, and were recruited to primary cutaneous melanoma lesions, in response to CCL20 produced in melanoma microenvironment." (PMID 39020402, 2024). "Stratification according to the suggested cutoff resulted in 54 melanoma patients in the low-CCL20 group (<0.34 pg/mL) and 47 in the high-CCL20 group (≥0.34 pg/mL)." (PMID 38730689, 2024). "The analysis using the log-rank test demonstrated that melanoma patients with high CCL20 have an impaired PFS with a median of 3 months (95% CI: 2–6) compared to patients with a low CCL20 with a median of 10.5 months (95% CI: 6–26) (p = 0.0033)." (PMID 38730689, 2024). "Our finding of CCL20 being an independent prognostic marker can be used as a biomarker for melanoma patients and has clinical relevance, as statements about the prognosis and therapy response can be made based on this." (PMID 38730689, 2024). "In the past, it has been demonstrated that melanoma cell lines express the CCL20 receptor C-C chemokine receptor type 6 (CCR6) and that the tumor-associated macrophages (TAMs) are the main source of CCL20 expression." (PMID 38730689, 2024). "Future prospective randomized trials are needed to establish CCL20 as a liquid biopsy-based biomarker in advanced melanoma." (PMID 38730689, 2024).
melanoma (continued). "In line with this, it was shown in the mouse model that B16 melanoma cells with CCL20 in CCR-sufficient mice lead to larger tumors compared to the injection of B16 melanoma cells without CCL20." (PMID 38730689, 2024). "Despite the demonstrated prognostic role of CCL20 in previous work, as well as our study, it would also be important to decipher the molecular mechanism in melanoma patients." (PMID 38730689, 2024). "Further, CCL20 was identified to be one of the most abundantly expressed chemokines in melanoma by analyzing the secretome of tumor-macrophage coculture." (PMID 38786066, 2024). "This analysis revealed 15 differentially expressed proteins (including CD31, VCAM-1, ANGPT2, CXCL8, and CCL20) in the hepatic endothelial cells after co-culture with melanoma cells." (PMID 37240247, 2023). "Increase the expression of CCL20;Reduce the recruitment of Th17 cells;Inhibit the lung metastasis of melanoma cells." (PMID 36140990, 2022). "For example, the chemokine CCL20 is recognized by the CCR6 ligand expressed in melanoma and promotes melanoma growth and metastasis in vivo." (PMID 36131942, 2022). "Using monocyte-derived macrophages, with either GM-CSF or with M-CSF, which are known to prime towards M1 or M2 phenotypes, we produced in vitro melanoma-conditioned macrophages expressing CCL20 and TNF (M1-primed) or VEGFA (M2-primed)." (PMID 34439098, 2021). "Our results highlight the role of TAMs in biologically aggressive primary melanomas, suggesting that prometastatic TAMs are characterized by higher secretion of CCL20/TNF/VEGFA cytokines." (PMID 34439098, 2021). "Rather than the number, size, or location of TAM, quantitative assessment of CCL20, TNF, and VEGFA cytokine content was associated with strong prognostic significance in primary melanoma." (PMID 34439098, 2021). "We had previously identified the expression of CCL20/TNF/VEGFA cytokines by TAMs in a pilot study with cryopreserved human melanoma tissues." (PMID 34439098, 2021). "Tissue expression of CCR6 and its ligand CCL20 (MIP-3a) were identified as progression predictors in primary melanoma patients." (PMID 33302400, 2020). "In comparison with melanocytes, primary melanoma subcutaneous and distant metastases all showed significantly increased CCL20 expression." (PMID 32601464, 2020). "All analysed melanoma cell lines exhibited higher expression of CCL20 compared with cultured human primary melanocytes, which express CCL20 only at a very low level." (PMID 32601464, 2020). "TNF-induced CCL20 is conferred by a region between -111 and -77, which contains a κB-like site in G-361 human melanoma cells." (PMID 27723802, 2016). "In melanoma, the profiling of GPCRs expressed by plasmacytoid DCs (pDCs) showed that the only significantly elevated GPCR is CCR6, which mediates the recruitment of pDCs from blood by the chemokine ligand CCL20 produced by melanoma cells." (PMID 25110692, 2014). "CCL20 is expressed by keratinocytes in the skin and by melanoma cells, suggesting that the CCL20/CCR6 interaction is involved in the pDC migration process from the blood to the tumor." (PMID 24282405, 2013). "In addition, our analysis has shown that LDH and S100, which are already implemented as laboratory characteristics to monitor melanoma patients, are significantly elevated in the high-CCL20 patient group (p = 0.004 and p = 0.049, respectively)." (PMID 38730689, 2024). "This study indicates the importance of CCL20/CCR6 axis for melanoma growth." (PMID 38786066, 2024). "Based on the observation in tissue, in this prospective study, we investigated whether the serum concentration of CCL20 in ICI-treated patients with advanced melanoma can predict the therapy response and overall survival (OS)." (PMID 38730689, 2024). "With regard to the reported activation of the Wnt/β-catenin signaling pathway via CCL20 in HCC, this may be a potential explanation for the impaired prognosis of high-CCL20 melanoma patients." (PMID 38730689, 2024).